ARNT (aryl hydrocarbon receptor nuclear translocator)
Diseases named in the same sentence as ARNT in open-access papers (continued):
Sharing a sentence is not in itself a finding about the gene and the disease.
cancer (103 papers, 2008 to 2026). A tumor composed of atypical neoplastic, often pleomorphic cells that invade other tissues. "A recent study confirmed the role of ARNT as a potential target in the treatment of cancer, which linked the expression of the bHLH PAS transcription factor with cisplatin resistance." (PMID 36859266, 2023). "Upregulation of ARNT/HIF-1-b has been associated with multiple types of cancer." (PMID 36915100, 2023). "Since we previously found that loss of the ARNT isoforms leads to modification of RelB DNA binding, we sought to investigate whether the ARNT isoforms depend on RelB for regulating cancer cell proliferation." (PMID 26909609, 2016). "Comparison of ARNT expression levels across these clusters identified enrichment in a subpopulation of cancer stem-like cells." (PMID 38806469, 2024). "Previous studies have demonstrated that ARNT expression is significantly upregulated in a variety of malignant tumors, including renal cell carcinoma, lymphoid cancer, multiple myeloma, breast cancer, and medulloblastoma." (PMID 38806469, 2024). "Accumulating evidence reveals that ARNT is upregulated in a variety of cancer tissues and cell lines, indicating the involvement of ARNT in tumorigenesis." (PMID 38806469, 2024). "Hypoxia-inducible factor-1 (HIF-1) complex, a kind of transcription factor composed of HIF-1α and ARNT (HIF-1β), can mediate and induce the Warburg effect in many types of cancer cells." (PMID 39883335, 2023). "MYC, SOX2, JUN, or ARNT was significantly correlated with THBS2 in most cancers, including COAD and PAAD." (PMID 34804159, 2021). "We also found that deregulation of ARNT enhances chemotherapeutic drug-induced cancer cell death through increased ROS levels." (PMID 33446631, 2021). "Some HIFs, such as HIF1A, ARNT, EPAS1, and HIF3A, were linked with unfavorable outcomes for pan-cancer, while two HIFs including ARNTL and ARNT2 were associated with favorable outcomes in pan-cancer." (PMID 33299416, 2020). "Deregulation of AHR and HIF-1α activity can promote various disease states including cancer proliferation, and ARNT has been shown to be essential in supporting these pathophysiological characteristics." (PMID 26909609, 2016). "ARNT has been shown to regulate the anti-oxidant response and resistance to chemotherapeutic drugs in diverse cancers and is important for AHR or HIF-1 promoted tumors." (PMID 26909609, 2016). "Collectively, these results revealed that ARNT down-regulation promoted cancer cell migration and invasion." (PMID 25839165, 2015). "Down-regulation of ARNT protein promoted cancer cell migration and invasion, which was mediated by activation of the fibronectin/integrin β1/FAK signaling axis." (PMID 25839165, 2015). "ARNT was amplified in almost all cancer cell lines, and its amplification was correlated with MCL-1 amplification (r2 = 0.9184)." (PMID 25839165, 2015). "Based on the observation that ARNT depletion enhanced cancer metastasis, we further investigated the mechanisms that were involved in the regulation of ARNT-mediated cell migration." (PMID 25839165, 2015). "Further, it have been demonstrated that the knockdown of ARNT in cancer cells reduced proliferation rate and the transformation ability and enhanced cisplatin-induced apoptosis." (PMID 25669983, 2015). "In this study, we found that ARNT plays further role in down-regulation of ROS to prevent cancer cells suffering damage from cisplatin treatment." (PMID 24921657, 2014). "Dimerization of hypoxia-inducible factor-1 beta (HIF-1β) [aryl hydrocarbon receptor nuclear translocator (ARNT)] with HIF-1α is involved in various aspects of cancer biology, including proliferation and survival under hypoxic conditions." (PMID 25068796, 2014). "Here, we found that knockdown of ARNT in cancer cells reduced the proliferation rate and the transformation ability of those cells." (PMID 24921657, 2014).
cancer (continued). "Consistent with our findings that ARNT was depleted by anti-cancer drugs, ARNT was also degraded by curcumin in normoxic and hypoxic conditions in various cancer cell types." (PMID 24921657, 2014). "In order to delineate the molecular mechanisms underlying AHR-mediated transrepression we sought to uncouple AHR and ARNT function in ER-positive human cancer cell lines." (PMID 22235307, 2012). "To trigger the similar Warburg effect with aerobic glycolysis of cancer cells in yeast, we integrated an expression cassette containing HIF-1α and ARNT genes, encoding the two subunits of HIF-1 complex, into the yeast chromosome of strain BY4741, deriving the strain XN01." (PMID 39883335, 2023). "Thus far, knocking down ARNT has been shown to suppress the expression of PDK1 (pyruvate dehydrogenase kinase in certain cancers." (PMID 34179020, 2021). "Interestingly, analysis of the Oncomine database revealed that ARNT is amplified in a number of diverse cancers." (PMID 26909609, 2016). "Importantly, depleting all ARNT isoforms with a common RNAi approach would be predicted to benefit cancer proliferation in the lymphoid malignancies examined." (PMID 26909609, 2016). "ARNT was also anticipated as a profound therapeutic target in certain types of cancer." (PMID 26572229, 2015). "Therefore, the expression of ARNT in tumors appears to be a prognostic biomarker and a target for cancer therapies." (PMID 25839165, 2015). "First, ARNT expression was analyzed using the cancer microarray database from Oncomine 4.0." (PMID 25839165, 2015). "Interestingly, reactive oxygen species (ROS) dramatically increased when ARNT was knocked down in cancer cells, enhancing cisplatin-induced apoptosis." (PMID 24921657, 2014). "Although the mechanism involved in regulation of ROS production by ARNT expression remains unknown, development of antagonists targeting the ARNT may provide new strategies for destroying resistant cancer cells." (PMID 24921657, 2014). "The identification of ARNT as a co-activator in estrogen signalling, juxtaposed with the known transrepressor effects of TCDD, led us to investigate the role played by ARNT in TCDD-mediated transrepression of ER function in various human cancer cell lines, namely MCF7 and ECC-1 cells." (PMID 22235307, 2012). "Normal B and cancer 1 clusters shared inflammatory markers CCL2, TNFRSF12A, and IL1R1, pathways including TNFα, IL, and Myc signaling, and activity of inflammation, hypoxia, and lipid metabolism–associated transcription factors NFATC2, ARNT, PPARA, and PPARGC1A." (PMID 40215177, 2025). "Interestingly, cisplatin-induced ARNT deregulation could also be reversed when different types of cancer cells were pretreated with the ROS scavenger NAC." (PMID 24921657, 2014). "Furthermore, ARNT is regulator involved in TF-miRNA feed-forward loop in cancer." (PMID 23293768, 2012). "The ERβ/HIF-1α/ARNT pathway may play an important role in cancer progression." (PMID 21435239, 2011). "Belzutifan is an FDA-approved anti-cancer medication that inhibits the HIF-2a signaling pathway by disrupting the protein-protein interaction between the HIF-2a transcription factor and the ARNT protein partner." (PMID 39452639, 2024). "All the significant nine representative terms covered 16 genes with 6 NCG cancer genes CTNNB1, PML, RB1, MLL2, ARNT and NRIP1 belonging to at least three representative terms." (PMID 34504716, 2021). "HIF-1β or Aryl hydrocarbon receptor nuclear translocator (ARNT) is constitutively expressed in most cells, but there is evidence that HIF-1α upregulates HIF-1β expression under hypoxia in some cancers." (PMID 32532126, 2020). "In the CHRNB4-high subgroup, CHRNB4 was co-expressed with numerous genes, such as ADCY9, NOTCH3, ARNT, NCOA1, and NCOA3, which correlated with multiple cancer-related processes, but only one gene, FLT4, was co-expressed in the CHRNB4-low subgroup." (PMID 32455963, 2020).
cancer (continued). "These four pathways were proteoglycans in cancer (ANK2, FASLG, HSPG2, PTPN11, STAT3, and VEGFA), HIF-1 signaling (ARNT, STAT3, and VEGFA), FoxO signaling (FASLG, SMAD4, and STAT3), and ECM-receptor interaction (HSPG2 and LAMA2)." (PMID 29300322, 2018). "It is interesting to note that ARNT is located at chromosome 1q21.3, a region that is amplified in several cancers with MCL-1 gene amplification and inhibits cancer cell apoptosis." (PMID 25839165, 2015). "However, the functional role of ARNT in chemotherapeutic drug-treated cancer remains unclear." (PMID 24921657, 2014). "Some cancer-related genes are located in these highly common, early appearing RARs: MCL1, CTSK, ARNT, S100A10, PTK2, PTP4A3, and PSCA in the RAR-Gs; and DLC1, PINX1, and GATA4 in the RAR-Ls." (PMID 22938721, 2012). "Most of these regions have been validated to encompass or closely near to cancer related genes such as MDM2, MYC, EGFR, ERBB2, CCND1, ARNT." (PMID 23285074, 2012). "We predict the differential expression of several transcription regulator genes (including HSF2, ARNT, MEF2A, ATF2 and YY1) that are strongly related to the cancer grade." (PMID 20025723, 2009). "We note this narrower CNA segment does not include the MDM4 oncogene, which is located at 1q32.1, thus other genes must be driving this recurrent genetic change in CNA-PC86, with possible candidates being known cancer genes BCL9 (1q21.2), ARNT (1q21.3), SETDB1 (1q21.3), or SF3B4 (1q21.2)." (PMID 41023738, 2025). "While the prolyl hydroxylation of HIFα is suppressed under hypoxia, leading to HIFα accumulation and heterodimerization with HIF1β (ARNT), which then binds the hypoxia response elements (HREs) to promote transcription of genes essential for cancer cell proliferation, angiogenesis, and etc." (PMID 41211480, 2025). "HIF-1, existing in the form of functional heterodimer which consisting of α and β (aryl hydrocarbon receptor nuclear translocator, ARNT) isoforms, is a primary sensor of oxygen limitation and its induction supports cancer cells proliferation during hypoxia by eliciting several metabolic alterations." (PMID 33109235, 2020). "The aryl hydrocarbon receptor (AhR) and aryl hydrocarbon receptor nuclear translocator (ARNT) complex is one of the transcription factors of NRF2, and the activity of this complex has been suggested to reduce cancer metastasis through increasing the expression of NRF232–34." (PMID 31527696, 2019). "To investigate whether the HMA-resistance-specific CNAs influence gene expression, we assayed the expression of 8 cancer-related genes by quantitative reverse transcription PCR (RT-qPCR) including BCL9, ARNT, ABL2, STK11, TCF3, SMARCA4, RUNX1, and U2AF1." (PMID 28052028, 2017). "ARNT serves as binding partner for several bHLH members and plays a key role in two distinct cellular signalling pathways – the AhR and HIF pathways - activated in response to environment stimulations and also largely involved in cancer cell biology." (PMID 25669983, 2015). "They find several cancer biology relevant genes, such as AKT1, ARNT, and PMS2 and their literature analysis finds that 57% of the BEDMRs overlap with at least one gene that has more than three literature references related to cancer." (PMID 24653980, 2014). "Previous studies have demonstrated that the anti-cancer properties of curcumin may be related to its ability to affect the HIF-1 pathway, affecting the expression of HIF-1α or by degrading ARNT (HIF1β) but without altering the expression and the transcriptional activity of HIF-1α." (PMID 30045750, 2018).
infection (12 papers, 2010 to 2024). The state of being infected such as from the introduction of a foreign agent such as serum, vaccine, antigenic substance or organism. "While HIF1α activation occurs in response to hypoxia and inflammatory signaling following infection, ARNT is constitutively expressed, and its regulation is less well characterized." (PMID 38897207, 2024). "The effect of arnT deletion in the infection process of S. Typhimurium was assessed in vitro by determining the level of adhesion and invasion in non-phagocytic Caco-2 cells." (PMID 38474006, 2024). "In the mammalian pathogen S. enterica, limiting Mg2+ encountered during infection induces EptA and ArnT synthesis for lipid A remodeling." (PMID 34361895, 2021). "In this prospect, the present investigation focused on studying the impact of arnT deletion in S. Typhimurium on multiple virulence factors such as initial infection and colonization, starvation sustainability, swarming, biofilm and associated phenotypes, host colonization, and survival." (PMID 38474006, 2024). "Overall, the in vivo results indicate that the initial infection in the gut by arnT was not impaired, but the systemic infection was considerably reduced." (PMID 38474006, 2024). "In LysMCreARNTf/f macrophages, only LPS plus parasites led to significant VEGF-A production that did not increase with DMOG, suggesting that some VEGF-A production during infection can be independent of ARNT/HIF-α signaling." (PMID 34959539, 2021). "However, the bacterial load in the ileum did not vary significantly, which implied that the arnT deletion may affect the invasion and infection in the liver and spleen but not the initial infection in the ileum." (PMID 38474006, 2024).
colorectal (1 paper, 2023). "We found that ARNT deficiency drives neutrophils recruitment, neutrophil extracellular trap (NET) development, inflammatory cytokine secretion and suppressive activities when cells enter the periphery from bone marrow upon colorectal tumorigenesis." (PMID 36859266, 2023).
psychiatric disorder (1 paper, 2018). A disorder characterized by behavioral and/or psychological abnormalities, often accompanied by physical symptoms. "The psychiatric disorder-associated variants p.Val304Ile and p.Ala552Pro were found to be normally expressed and localized to the nucleus, and further, did not affect interaction with ARNT, nor regulation of the VGF reporter construct relative to wild-type." (PMID 30509165, 2018).
ARNT also shares sentences with these, for which no sentence is quoted: lung carcinoma (5 papers); endometrial carcinoma (4); pulmonary hypertension (3); Stroke (3); cardiac ischemia (2); Chronic myeloid leukemia (2); epidermoid carcinoma (2); gastrointestinal stromal tumor (2); Heart Disease (2); Hyperglycemia (2); hyperlipidemia (2); lymphoid cancer (2); rheumatoid arthritis (2); schizophrenia (2); steatosis (2); Uterine leiomyoma (2); acute myocardial infarction (1); adenovirus infection (1); amyotrophic lateral sclerosis (1); Anxiety (1); anxiety disorder (1); asphyxia (1); autism (1); autoimmune disease (1); benign prostate hyperplasia (1); bipolar disorder (1); bladder cancer (1); cardiovascular disease (1); chordoma (1); cutaneous melanoma (1).
A further 35 diseases each share a sentence with ARNT in 1 paper.